CYP3A4 (cytochrome P450 family 3 subfamily A member 4)
Diseases named in the same sentence as CYP3A4 in open-access papers (continued):
Sharing a sentence is not in itself a finding about the gene and the disease.
Obesity (continued). "There are no data on apixaban exposure related to CYP3A4 activity in patients with obesity; thus, the clinical importance of this is uncertain." (PMID 38822847, 2024). "Furthermore, and in agreement with a previous study in patients with NAFLD and obesity, we observed a weak inverse correlation between NAFLD liver fat score and 4βOHC concentrations, suggesting decreased CYP3A4 activity in patients with NAFLD." (PMID 35648149, 2022). "In contrast, other factors might explain why obesity and NAFLD are not always associated with more frequent or more severe APAP-induced acute hepatotoxicity, such as increased volume of distribution in the body, higher hepatic glucuronidation and reduced CYP3A4 activity." (PMID 36713231, 2023).
rhabdomyolysis (37 papers, 2012 to 2026). Necrosis or disintegration of skeletal muscle often followed by myoglobinuria. "Inhibition of CYP3A4 can elevate plasma statin concentrations, heightening the risk of adverse effects such as myopathy and rhabdomyolysis, particularly for statins with low oral bioavailability." (PMID 41011221, 2025). "Co-administration is associated with an increased risk of myopathy and rhabdomyolysis, as CsA can inhibit CYP3A4 activity and increase simvastatin’s AUC." (PMID 40927301, 2025). "A well-known example of this is GFJ, which increases plasma levels of several CYP3A4 substrates, including simvastatin, thereby enhancing the risk of adverse effects such as myopathy and rhabdomyolysis." (PMID 41011221, 2025). "Conversely, grapefruit juice inhibits CYP3A4, which can increase statin levels and elevate the risk of myopathy and rhabdomyolysis." (PMID 40867897, 2025). "Statins have significant CYP3A4 interactions with PIs, which increase the concentration of statins, increasing the risk of adverse events such as rhabdomyolysis." (PMID 35215140, 2022). "Posaconazole is also an inhibitor of CYP3A4, which increase the risk of rhabdomyolysis if used with statins together." (PMID 35313994, 2022). "The co-administration of CYP3A4 inhibitors with atorvastatin showed a higher risk of muscular adverse events such as myopathy and rhabdomyolysis." (PMID 34867368, 2021). "An important example is the impact of PIs boosted with ritonavir or cobicistat on the exposure of several statins via inhibition of CYP3A4 and/or hepatic transporters thereby increasing the risk of myopathy or rhabdomyolysis." (PMID 32011104, 2020). "The risk of rhabdomyolysis in patients using statins increases with the concurrent use of CYP3A4 inhibitors such as antifungal agents (itraconazole, ketoconazole, and fluconazole) or macrolide antibiotics (erythromycin and clarithromycin)." (PMID 32947890, 2020). "Clarithromycin inhibits cytochrome P450 enzyme 3A4 (CYP3A4), which was associated with a doubled risk of hospitalization with rhabdomyolysis or other statin‐related AEs according to a systematic review recently." (PMID 32548932, 2020). "For example, cotreatment with simvastatin and fluconazole, a known CYP isoenzyme 3A4 (CYP3A4) inhibitor, can cause rhabdomyolysis in patients likely due to elevated plasma levels of simvastatin." (PMID 26557399, 2015). "Previous research has demonstrated that the ratio of adverse event reporting of rhabdomyolysis associated with simvastatin stratified by concomitant use of CYP3A4 inhibitor was 6.3." (PMID 25932626, 2015). "This metabolic profile makes atorvastatin vulnerable to interactions with CYP3A4 inhibitors, such as itraconazole, ritonavir, and GFJ, potentially raising systemic drug levels and the risk of adverse effects like myopathy or rhabdomyolysis." (PMID 41011221, 2025). "Several statins widely used in clinical practice, such as atorvastatin, simvastatin, and lovastatin (and previously cerivastatin, now off the market because of very high incidence of rhabdomyolysis), are metabolized by the cytochrome P450 (CYP)3A4 pathway." (PMID 35955495, 2022). "It is also shown that in statin-induced rhabdomyolysis, there is in 2/3 of cases concomitant treatment with a drug that inhibits CYP3A4." (PMID 31640597, 2019). "The reported case of rhabdomyolysis was most likely induced by Palbociclib-inhibition of the CYP3A4 enzyme, resulting in increased toxic levels of plasma concentration of Simvastatin." (PMID 31640597, 2019). "We describe a particularly severe case of rhabdomyolysis after the introduction of ciprofloxacin, a weak CYP3A4 inhibitor, in a patient who previously tolerated the simvastatin-amlodipine combination." (PMID 25883814, 2015). "In this analysis, 8 patients with rhabdomyolysis had concomitant administration of CYP3A4 inhibitors (verapamil, diltiazem, amiodarone, lercanidipine, aprepitant, and clarithromycin)." (PMID 22484722, 2012).
rhabdomyolysis (continued). "Additionally, a 2012 United Kingdom study found that the interaction of a CYP3A4-metabolized inhibitor with a CYP3A4-metabolized-statin accounted for approximately 30% of patients with statin-induced rhabdomyolysis." (PMID 39330354, 2024). "Due to its reliance on CYP3A4, co-administration with potent inhibitors such as erythromycin, ketoconazole, or GFJ may substantially increase plasma concentrations, elevating the risk of muscle-related adverse events, including rhabdomyolysis." (PMID 41011221, 2025). "This ADE is most likely the result of a drug-drug interaction (DDI) between ticagrelor and statins because ticagrelor is a CYP3A4 substrate and a weak inhibitor of CYP3A4, which may lead to increased concentrations of statins such as simvastatin, leading to rhabdomyolysis." (PMID 38655177, 2024). "In this case, replacement of treatments with appropriate alternatives, such as the use of a different statin not metabolized through the CYP3A4 pathway or changing the antihypertensive treatment regimen, can reduce the risk of serious complications such as rhabdomyolysis." (PMID 38646234, 2024). "Statins are also metabolized by CYP3A4; therefore, high doses of lomitapide may suppress statin clearance by CYP3A4 and, as a result, expose the organism to serious side effects related to excessive statin exposure, such as myopathy and rhabdomyolysis." (PMID 39777225, 2024). "Ranolazine can inhibit CYP-mediated metabolism (CYP3A4) and/or transport proteins and thus lead to increased plasma levels of drug substrates and potential ADRs such as lactic acidosis when coadministered with metformin or myopathy and rhabdomyolysis with simvastatin." (PMID 33572247, 2021).
Hypertension (33 papers, 2014 to 2025). The presence of chronic increased pressure in the systemic arterial system. "The A allele of CYP3A4 rs4646437 was associated with an increased risk for hypertension (OR=1.36, 95% CI: 1.12–1.66, P=0.002)." (PMID 30910847, 2019). "In the present study, we found that the A allele genotype of CYP3A4 rs4646437 can increase the risk of hypertension compared with G allele genotype." (PMID 30910847, 2019). "A study from Chinese population indicated that the CYP3A4 gene polymorphism was associated with hypertension." (PMID 30910847, 2019). "Using a case–control design, we assessed the association between single nucleotide polymorphisms of CYP3A4 gene rs4646437 polymorphism and the risk of hypertension in Chinese population." (PMID 30910847, 2019). "The present study investigates the association between single nucleotide polymorphisms of CYP3A4/ rs4646437 gene and hypertension in the Chinese Han population." (PMID 30910847, 2019). "Sex, age, smoking, allergic history, family chronic disease and CYP3A4*1G mutation were analyzed as exposure variables and alcoholic abuse, malignant disease, hypertension, heart disease, diabetes and dyslipidemia were analyzed as outcomes in logistic regression analysis." (PMID 38117809, 2023). "Cortisol is metabolized by CYP3A4 such that the use of antihypertensive medications, such as CCBs, might affect the association of hypertension with refractory subretinal fluid." (PMID 35743446, 2022). "Our results revealed a possible genetic association between CYP3A4 gene rs4646437 and hypertension, and the AA genotype of rs4646437 increased the risk of hypertension in Chinese Han population, and this effect could be confirmed by multivariable analyses." (PMID 30910847, 2019). "In conclusion, we found that the CYP3A4 gene rs4646473 polymorphism was related to the risk of hypertension in the Chinese population, and this effect could be confirmed by multivariable analyses." (PMID 30910847, 2019). "Having considered the drug metabolism function of CYP3A4, the rs4646437 may be a potential treatment target for hypertension with A allele mutation." (PMID 30910847, 2019). "Recently, previous study reported that the A-allele of CYP3A4 rs4646437 was associated with an increased risk for hypertension (odds ratio [OR]=2.4, 95% confidence interval [95% CI]: 1.10–5.20, P=0.021) in metastatic renal cell carcinoma patients treated with sunitinib." (PMID 30910847, 2019). "This may partly explain the potential mechanism of CYP3A4 associated with hypertension." (PMID 30910847, 2019). "Nisoldipine, a cardiovascular medication mainly used to manage hypertension, is primarily metabolized in humans by CYP3A4." (PMID 39329117, 2024). "Our results suggest that the GG genotype for rs2242480 in CYP3A4 and CC genotype in rs776746 for CYP3A5 were both associated with the presence of hypertension." (PMID 36982571, 2023). "In summary, the essential contraindications for ubrogepant include hypersensitivity to the drug, severe hepatic impairment, concurrent use of potent CYP3A4 inhibitors, pregnancy or breastfeeding, and uncontrolled hypertension." (PMID 38046695, 2023). "We observed that at genotype level, the rs2242480 in CYP3A4 (GG) and the rs776746 in CYP3A5 (CC) were significantly associated with the presence of hypertension (p = 0.02)." (PMID 36982571, 2023). "Felodipine, an anti-hypertensive agent that is exclusively a CYP3A4 substrate, has been demonstrated to cause changes in sorafenib pharmacokinetic parameters in an 80-year-old HCC patient with hypertension." (PMID 34681219, 2021). "Calcium channel blockers (CCBs), which are used in patients with hypertension, were also metabolized by CYP3A4." (PMID 32548932, 2020). "Hence, the CYP3A4 rs4646437 may be associated with occurrence of hypertension." (PMID 30910847, 2019).
Hypertension (continued). "However, specific contraindications, such as hypersensitivity, severe hepatic impairment, concurrent use of CYP3A4 inhibitors, pregnancy or breastfeeding, and uncontrolled hypertension, require caution or avoidance of ubrogepant." (PMID 38046695, 2023). "There was no statistical significance association between hypertension, type 2 diabetes or dyslipidemia and the CYP3A4*1G genetic mutation." (PMID 38117809, 2023). "However, some contraindications exist, including hypersensitivity, severe hepatic impairment, concurrent use of CYP3A4 inhibitors, pregnancy/breastfeeding, and uncontrolled hypertension." (PMID 38046695, 2023). "Currently, the potential biological mechanism by which the CYP3A4 gene affects the progression of hypertension still remains unclear." (PMID 30910847, 2019). "Finally, the present study explored the relationship between CYP3A4 and hypertension using epidemiology, and the molecular mechanisms need to be confirmed." (PMID 30910847, 2019). "As a synthesis enzyme of cholesterol, CYP3A4 closely connects to high blood pressure." (PMID 30809144, 2019). "Sunitinib-induced hypertension may be related to SNPs in cytochrome P450 3A4 (CYP3A4) that transform sunitinib -to its active metabolite." (PMID 27941701, 2016). "The commonly prescribed drugs for hypertension (Propranolol, Metoprolol, Telmisartan, Losartan) and T2DM (Glimepiride, and Pioglitazone) shares the same drug metabolizing enzymes (CYP1A2, CYP3A4, CYP2C9, and CYP2D6)." (PMID 34115763, 2021). "CYP3A4, APOA2, PPARG, ALOX, and CYP4F2, proteins related to lipid homeostasis affect the occurrence of hypertension, and PTGER2, ALOX5, LTF, ITGB, and GATA3 relate to the inflammatory and immune response in glomeruli." (PMID 30809144, 2019).
diabetes (28 papers, 2009 to 2025). "Though patients on antiretroviral therapy were not stated to be included, a Japanese case-control study indicated that CYP3A4 (13989A>G) polymorphism is associated with the prevalence of type 2 diabetes mellitus." (PMID 35887584, 2022). "Nonetheless, regarding the possible association of CYP3A4 with diabetes mellitus, experimental clinical data are inconsistent." (PMID 36359206, 2022). "Recent research articles have elucidated the relation between CYP3A4 polymorphisms and type 2 diabetes mellitus by showing that people with some CYP3A4 polymorphisms are at a higher risk of type 2 diabetes mellitus." (PMID 36359206, 2022). "For instance, one study in 2011 indicated diabetes is associated with a significant decrease in hepatic CYP3A4 enzymatic activity and protein level." (PMID 34863089, 2021). "Female sex, history of diabetes, and use of a CYP3A4 or Pgp inhibitor (moderate or strong) were also associated with higher anti-Xa activity (p < 0.001,p = 0.011, andp = 0.002, respectively)." (PMID 31249919, 2017). "In diabetes, a significant reduction in CYP3A4 has been observed, resulting in reduced CYP3A4 dependent clearance." (PMID 36942294, 2023). "It is these acids, not insulin, that raise the activity and mRNA and protein expression of CYP3A4, as demonstrated in vitro on HepG2 and Fa2N-4 cells that are incubated with the serum of rats with streptozotocin-induced diabetes." (PMID 36359206, 2022). "During investigation into the expression of hepatic CYP enzymes in patients with diabetes mellitus, the results revealed that this disease correlates with a significant decrease in hepatic CYP3A4 enzymatic activity and protein levels." (PMID 36359206, 2022). "Fatty acids (palmitic, oleic, stearic, and linoleic) participate in the mechanism of CYP3A4 induction in experimental diabetes." (PMID 36359206, 2022). "For example, it has been reported that the functional activity and expression of CYP3A4 are higher in experimental diabetes." (PMID 36359206, 2022). "Another identified differentially expressed gene, CYP3A4, belongs to the cytochrome P450 family, and the presence of these enzymes contributes to low chronic inflammation in type 2 diabetes mellitus." (PMID 36051390, 2022). "Diabetes also changes the experesion of cytochrome P450 enzymes, including CYP3A4, CYP2E1, CYP2C9, and CYP2D4 participate in phase I drug metabolism." (PMID 32467722, 2020). "In an analysis restricted to patients taking 5 mg BID, we found renal function, age, sex, body weight, diabetes, heart failure, and use of inhibitors of CYP3A4 or P-gp to be independent clinical predictors of trough apixaban levels." (PMID 31249919, 2017). "The treatment of diabetes mellitus often demands the use of several drugs whose metabolism often depend on CYP3A4." (PMID 25835492, 2015). "Among the 7 patients in the simvastatin group, 4 were also taking CYP3A4 inhibitors (2 on erythromycin and 2 on verapamil), and one other had chronic renal failure and diabetes." (PMID 19442259, 2009). "Moreover, certain foods and herbal supplements can also inhibit or induce CYP3A4 activity, complicating the management of diabetes therapy." (PMID 41011221, 2025). "The liver is the key site of drug metabolism; therefore, reduced activity and expression of CYP3A4 may enhance the therapeutic effects of CYP3A4 substrates in diabetes mellitus." (PMID 36670981, 2023). "It's important to note that ritonavir, as a strong CYP3A4 inhibitor, may affect the metabolism of various drugs used for arrhythmia, diabetes, and neurological diseases, even when nirmatrelvir/ritonavir is used for a short duration." (PMID 37900159, 2023). "Diabetes reduces the activity of CYP3A4 and may increase the exposure for the drugs metabolized by the isoenzyme." (PMID 32016844, 2020). "Furthermore, studies revealed the evidence of hepatic CYP3A4 induction in diabetes." (PMID 36670981, 2023).
diabetes (continued). "Several lines of evidence have also supported the role of the secondary genes FMO1 and ALOX1 having interaction with CYP3A4 and PTGS1 in diabetes mellitus." (PMID 36051390, 2022). "A study using human liver samples obtained from diabetic and nondiabetic donors suggested that diabetes is associated with a significant decrease in hepatic P450 3A4 enzymatic activity and protein level and that CYP3A4 dependent drug metabolism may be decreased in this group of patients." (PMID 25835492, 2015). "Of relevance, many diabetes drugs are metabolized by CYP2C9, CYP3A4, and CYP2C8." (PMID 36285162, 2022). "Diabetes patients were also reported to show a trend to increase in the expression and activity of CYP3A4, although no statistical significance was observed." (PMID 32290519, 2020). "Adjusting for CYP3A4 and CYP3A5 variation, BMI, smoking status, diabetes, CKD, and race did not significantly impact this finding." (PMID 41295213, 2025).
liver disease (23 papers, 2008 to 2024). "Among them, hepatocyte function-related genes, such as ALB and CYP3A4, as liver-disease risk factors, were downregulated in aged liver." (PMID 37378670, 2024). "We investigated whether the CYP3A4*22 (rs35599367) variant, which reduces the metabolism of statins, affects liver disease outcomes in people who take statins (eTable 5 in Supplement 1)." (PMID 37358849, 2023). "EV cytochrome P450 family 3 subfamily A member 4 (CYP3A4) is also positively related to drug-induced liver diseases, such as rifampin, herbal products and, phenobarbital." (PMID 39396032, 2024). "CYP3A4 is a prominent drug-processing gene involved in the metabolism of a variety of commonly used drugs and is thought to contribute to bile acid metabolism during liver diseases." (PMID 32101552, 2020). "Increased ASV exposure could arise from the severity of liver disease, which attenuates the hepatotropic disposition of ASV via reductions in CYP3A4-mediated metabolism, OATP transport, and hepatic blood flow." (PMID 31291311, 2019). "Consequently, these combined findings indicate that starting doses of CYP2D6, CYP2E1 and CYP3A4 substrates should be adjusted in patients with moderate or severe liver disease, whereas a dose reduction of CYP2C19 and CYP1A2 substrates should already be considered in milder forms of liver disease." (PMID 27754327, 2016). "In patients without a clinically significant liver disease, investigation into the effect of chronic hepatitis C on pharmacokinetics of a probe of CYP3A enzymes called midazolam has uncovered weaker CYP3A4 activity in patients with chronic hepatitis C than in healthy volunteers." (PMID 36359206, 2022).